CD34 (CD34 molecule)
Diseases named in the same sentence as CD34 in open-access papers (continued):
Sharing a sentence is not in itself a finding about the gene and the disease.
tumor (continued). "Although CD34+CD90+ ECs are endothelial, they exhibited numerous mesenchymal-associated features, promoted tumor metastasis, and were associated with poor patient prognosis, suggesting the possibility of a link to CAF biology." (PMID 41154806, 2025). "As expected, given their generally relatively high abundance, αSMA+ fibroblasts, CD68+/CD163- macrophages, and CD31+/CD34+ endothelial cells were near each other, tumor cells, and T cells across all molecular subgroups examined." (PMID 39969434, 2025). "Immunohistochemically, tumor cells showed patchy staining of CD34 and S100 protein, with weak focal staining for α- SMA, calponin, and Bcl-2." (PMID 40548109, 2025). "Bone marrow biopsy revealed the presence of tumor cells, and immunohistochemical staining showed that the tumor cells were positive for CD34, MPO, and CD99, and weakly positive for PAX-5, suggesting a diagnosis of AML." (PMID 41561755, 2025). "Subsequent histological examination (H&E) and mIHC of tumor lesions revealed that CD34+CLDN5+ ECs significantly contributed to the development of CCA within HCC." (PMID 39674501, 2025). "Immunohistochemical analysis revealed moderate diffuse membrane expression of the anti-CD34 antibody in the tumor cells, as well as moderate and diffuse nuclear expression of the anti-STAT6 antibody." (PMID 40065864, 2025). "Neuronal nuclear antigen, calcineurin, tyrosine hydroxylase and CD34 are other markers found in these tumours." (PMID 40013208, 2025). "The results showed that two cases diagnosed as superficial CD34-positive fibroblastic tumor and two cases diagnosed as undifferentiated pleomorphic sarcoma have PRDM10 gene rearrangement." (PMID 40560238, 2025). "A biopsy of the lesion was performed, and pathology revealed an atypical epithelioid and hypercellular storiform spindled cell proliferation with scattered giant cells and CD34-positive tumor cells." (PMID 40525207, 2025). "Tumor growth inhibition was observed in studies utilizing humanized mice treated with anti‐PD‐1 antibody, recreated with cord blood‐derived CD34+ cells, and transplanted with tumor tissue." (PMID 40145271, 2025). "We analyze microvessel density and CD34 expression levels to assess tumor malignancy and patient prognosis." (PMID 40892951, 2025). "CD34-positive lymphatic vessels were found not only in the deepest infiltrated zone but also in the tumor center." (PMID 40243510, 2025). "CD34+ tumor blasts were often detected in starting materials, exceeding 50% in several apheresis products." (PMID 39858024, 2025). "The anti-tumor efficacy of 22.0405.aF was assessed in human CD34+ hematopoietic stem cell (huHSC) humanized NCG-hIL15 mice inoculated subcutaneously with JeKo-1 cells on the right flank/shoulder." (PMID 41479906, 2025). "The tumor cells exhibited an endothelial cell phenotype with diffuse strong positivity for CD34, CD31, ERG, and FLi-1, and diffuse and strong nuclear reactivity to TFE3." (PMID 39917171, 2025). "In accordance with myofibroblastic differentiation of the tumor, positive staining for smooth muscle actin, desmin, vimentin, and CD34 is typically observed." (PMID 40797454, 2025). "Significantly higher tumour necrosis and apoptosis, and significantly lower Ki67, CD34 and VEGFR2 staining, was determined from the cabozantinib-treated mice." (PMID 40359728, 2025). "Using single-cell RNA sequencing, we identified a distinct senescent-associated subset of endothelial cells (ECs), namely CD34+CLDN5+ ECs, which mainly enriched in tumor tissue." (PMID 39674501, 2025). "Staining for vimentin and CD34 highlights the cytoplasmic projections of these characteristic tumor cells, giving them a distinct dendritic appearance." (PMID 41458523, 2025). "We examined the correlations between expression of CD4, CD8, and CD34 and tumor margin infiltration observed on a DWI sequence." (PMID 40362599, 2025).
tumor (continued). "In orthotopic xenograft models, HepG2-HHLA2 cells exhibited accelerated intrahepatic tumor growth and increased CD34 + microvascular density compared to HepG2-Vec controls." (PMID 40394703, 2025). "Next, T-cell proliferation was assessed in co-cultures with effector cells, CD34+ HSCs, unpulsed DCs, or tumor-antigen-pulsed DCs at Effector cell/T cell ratios of 1:1, 1:2, 1:4, and 1:8." (PMID 41295503, 2025). "Pathology from the first Mohs stage confirmed hybrid DFSP and GCF, with CD34 positivity highlighting the tumor cells on all blocks." (PMID 40525207, 2025). "The tumor cells were diffusely CD34, ERG, and focally p63 reactive, while S100 protein, cytokeratin AE1/AE3, Pan-TRK, ALK, smooth muscle actin, and desmin were negative." (PMID 40878874, 2025). "On Immunohistochemistry (IHC), tumor cells show positivity for vimentin, with variable reactivity for actin, desmin, and CD34." (PMID 40092021, 2025). "The final model included invasion, edge type, Ki-67, tumor shape, mitotic index, CD-34, 17 radiomic features, and 6 deep learning features." (PMID 40571854, 2025). "The results showed the presence of CD34+CLDN5+ positive cells in tumor tissue, while these cells were scarcely observed in peri-tumor tissue." (PMID 39674501, 2025). "An elevated count of immunosuppressive CD34+ progenitor cells is detected in both peripheral blood and tumor tissues." (PMID 41246358, 2025). "To determine the characteristics of the vessel structures within the tumor stroma, we examined the lengths of CD34+ and CD105+ vessel structures in MOC1 and MOC2." (PMID 41210695, 2025). "The tumor demonstrates variable CD34 and/or S100 immunohistochemical expression, frequently with co-expression of CD34 and S100." (PMID 40548109, 2025). "Post-operation, a histopathological assessment of the specimen was performed which returned positive for tumor markers CD34 and ERG." (PMID 40541022, 2025). "Simultaneous immunostaining The CD34/CK-HMW analysis revealed a reduction in the number of stromal epithelial cells that correlated with the growth of capillary structures in tumor development." (PMID 39997620, 2025). "An alternative approach is the use of humanised CD34+ haematopoietic stem cell-reconstituted mice harbouring human EWS tumours." (PMID 41154376, 2025). "In our patient's case, the tumor's spindle-cell morphology and positive staining for CD34 and STAT6 confirmed the diagnosis." (PMID 40672405, 2025). "The number of CD68- and CD34-positive cells per 1.38 × 105 μm2 in the deepest infiltration zone and tumor center, respectively, was measured at multiple locations in each case, and the mean values were determined." (PMID 40243510, 2025). "Results from coculture and cell transfer assays suggest that cancer cachexic CD45+ erythroid progenitor cells (EPCs) induce the death of CD34+ progenitor cells and decrease the number of LtβR+, Mmp9+ and Ccl19+ mFbs in tumour‐free mice." (PMID 40665793, 2025). "Given that a minority of tumor cells express CD34, the possibility of B‐cell lymphoblastic lymphoma must still be considered." (PMID 41347016, 2025). "We thereby established a correlative CCI network and identified strong interactions between tumor cells and Fbs that were CD34+, MMP3+, or APOE+." (PMID 40126353, 2025). "We further performed immunohistochemical staining on tumor tissues to assess the expression levels of PD-1, E-cadherin, and CD34." (PMID 40568595, 2025). "A unique cluster of tumor cells in D‐TGCT is identified that regulated differentiation of CD34+ fibroblasts into MMP3+ fibroblasts or APOE+ fibroblasts via COL6A3 − (ITGAV + ITGB8) interaction." (PMID 40126353, 2025). "CD34 is a marker of mature microvessels in differentiated tumors, and we found that a high abundance of CD34 positive microvessels reduced tumor invasion and improved patient prognosis." (PMID 39906069, 2025).
tumor (continued). "Immunohistochemical studies can further support the diagnosis, with the tumor cells typically expressing CD34, which is a marker of fibroblastic differentiation." (PMID 39803158, 2024). "Paired PBMC and tissue samples from patients undergoing tumor resection were analyzed by flow cytometry to assess tissue entry and compare phenotype and developmental potential of Lin-CD34+DNAM-1bright CXCR4+ cells in both compartments." (PMID 38390333, 2024). "Immunohistochemical staining revealed that the tumor cells were diffusely and strongly positive for CD34 and D2-40." (PMID 39559587, 2024). "To elucidate the change in tumor vascularization, we performed CD34 immunostaining in xenografted tumor tissue." (PMID 38673992, 2024). "For example, CD34, a marker of vascular endothelial cells, was found to evaluate the capillarization of sinusoids and tumor neo-vascularization." (PMID 38960952, 2024). "In functional assays, we showed that proliferation and anti-tumor reactivity of CD34+ progenitor-derived NK cells are significantly affected by TGF-β1 exposure." (PMID 39376560, 2024). "Next, we verified the expression of A20/ACSL4 in the tumor by immunohistochemistry, the expression of the ferroptosis marker PTGS2, and the obvious effect of Apatinib + miR-214-3p inhibitors on tumor angiogenesis by CD34." (PMID 38370339, 2024). "Elevated MVD, indicated by CD31 and CD34 expression, correlates with aggressive tumor behavior, suggesting a potential mechanism for BCC growth and metastasis potential." (PMID 39399171, 2024). "A reconstruction of the vasculature in 3D allowed us to analyze the CD34 density, vessel length, total vessel length per volume, vessel radius, and vessel tortuosity for each tumor." (PMID 39133649, 2024). "Up to now, immunohistochemical staining has usually shown that tumor cells differentially express CD34, BCL-2, wave proteins and CD99, which are almost always positively or strongly positively expressed in SFT." (PMID 39015488, 2024). "The tumor cells expressed mature B cell-associated antigens CD20 and CD79a, and the vascular endothelial markers CD31 and CD34 showed that the tumor cells were filled in the blood vessels, infiltrated blood vessel walls, and perivascular areas." (PMID 39414604, 2024). "To examine the clinical significance of our findings, we also performed triple‐immunostaining of CD34, α‐SMA, and YY1 on tumor sections derived from our EGFR mutated NSCLC patient cohort." (PMID 39435643, 2024). "TLS presence and a high number of immature stromal blood vessels (IBV, CD34+/SMA-) were significantly correlated with a low percentage of αSMA-positive tumor cells." (PMID 39698197, 2024). "Together, the mIHC, scRNA-seq, and spatial transcriptomic data reveal that tumor regions are not only highly enriched with CD34+ tumor endothelial cells, but also have VEGFA+ PVM that interact with these endothelial cells in that region." (PMID 39761010, 2024). "Immunohistochemistry staining revealed diffuse positive expression of STAT6 and CD34 in the tumor cells." (PMID 38388450, 2024). "The significance of immunohistochemical markers such as CD31, CD34, Melan-A, and D2-40, provide unique insights into the tumor’s biological behavior and prognosis." (PMID 39399171, 2024). "On IHC, atypical spindle cell/ pleomorphic lipomatous tumor shows variable positivity for CD34, S100 protein, and desmin, while MDM2 and CDK4 are often negative." (PMID 38916002, 2024). "The immunohistochemical evaluation demonstrated the expression of vimentin, CD34, apolipoprotein D, and nestin in tumor cells." (PMID 39803158, 2024). "The tumor cells were diffusely and strongly positive for CD34 and D2-40, and anti-human herpesvirus 8 (HHV8) staining showed positive granular nuclear staining." (PMID 39559587, 2024). "The tumor displayed focal or patchy CD34 immunoreactivity, suggesting trichilemmal differentiation from the outer root sheath, with most of the cells negative for CD34." (PMID 39727620, 2024).
tumor (continued). "As expected, lenvatinib reduced the number of blood vessels identified by CD34 + /PAS + staining of subcutaneous murine tumor sections." (PMID 38635031, 2024). "Overall, CD31+ and CD34+ cells were much more abundant within cancer tissue as compared to tumor-adjacent adipose tissue." (PMID 39456610, 2024). "Some cases of FSDF show positive staining for CD34; however, staining areas are less diffuse and usually observed at the periphery of the neoplasm." (PMID 39206338, 2024). "In the tumor-immune cell analysis, the immune system had more predicted interactions with CD34+ cells expressing higher than lower BCR-ABL1 pathway activity." (PMID 37919606, 2024). "CD34 is a currently recognized sensitive marker of tumor neovascular endothelium, which is present in the endothelial cells of microvessels." (PMID 38771398, 2024). "Specifically, stem-like OC cells expressing CD34+ and VE-cadherin+ markers were capable of generating xenograft tumours containing blood vessels lined with human CD34+ cells." (PMID 38892471, 2024). "Double IHC staining for Keratin 7 and CD34 revealed that Keratin 7-positive tumor cells were accompanied by CD34-positive hepatic sinusoid-like vessels, mimicking the original structure of the hepatic plate." (PMID 38960952, 2024). "Nearly all patients appearance of structural disorder in the center of the tumor and the adjacent cortex, and there is also a dendritic positive pattern of immunohistochemical CD34." (PMID 39634774, 2024). "MVD evaluated by Nestin showed more associations with larger tumors, high-grade tumors, wider tumor extension, advanced stage, and metastasis than MVD measured by CD34." (PMID 39687450, 2024). "S-100 protein was focally positive in the tumor cells, and CD34 was positive in the walls of blood vessels." (PMID 39473659, 2024). "According to the results of CD34 immunohistochemical staining in tumor tissue, the PLA-drug group had a significant reduction in the expression of CD34 protein in tumor tissue compared with the other three groups." (PMID 38526656, 2024). "Immunohistochemistry and immunofluorescence analyses show that the expressions of IDO1 and CD34 in tumor tissues of RY103-treated mice were reduced." (PMID 39065567, 2024). "In terms of immunohistochemistry, DOG1 and CD117 antibodies are widely considered to be the most sensitive and specific markers in the diagnosis of GIST, and CD34 is often used to distinguish GIST from other tumor biomarkers." (PMID 38395931, 2024). "To measure tumor vascularity, we performed IHC using anti-murine CD34 to stain blood vessels and anti-murine LyVE-1 to stain lymphatic vessels." (PMID 39594584, 2024). "Extensive tumour staining for CD34 is typical and is a feature that has a limited differential diagnosis (principally PXA, ganglioglioma and PLNTY)." (PMID 39294363, 2024). "Immunohistochemistry showed that tumor tested positive for CD34(+), STAT-6(+), and Ki-67 (10%) and negitive for SMA, Desmin, S-100, EMA, DOG1, CD117, TLB1, CDK4, Pax-8, MDM2, Myogenin, and CD31." (PMID 39121255, 2024). "Some spindle or star‐shaped cells in the tumor capsule and Antoni B region exhibit CD34 positivity and S‐100 protein negativity, with the opposite expression pattern in the Antoni A region." (PMID 39158355, 2024). "Tumor size, gastrointestinal bleeding, mitotic index, NIH risk category, CD34, and Ki-67 all exhibited an obvious correlation with PVPR (all p < 0.05)." (PMID 39582542, 2024). "In our case, CD34 positivity was found focally by the examination of the entire tumor in a radical prostatectomy specimen." (PMID 39768800, 2024). "The chemo-immuno-sensitizing effects of nanoparticles encapsulating zoledronic acid (NZ) on shTFEB tumors and on tumor immune-microenvironment were evaluated in Hu-CD34+ mice by single-cell RNA-sequencing." (PMID 39107857, 2024).
tumor (continued). "Pan-Trk immunoreactivity is associated with a fusion partner-specific pattern of staining NTRK-rearranged tumours also commonly express CD34, often with coexpression of S100, but lack SOX10 expression." (PMID 38151535, 2024). "Mice treated with αCD20-EndoP125A demonstrated a significant reduction in the total amount of both CD34+ and LyVE-1+ tumor vessels compared to all other treatments." (PMID 39594584, 2024). "Immunohistochemical results showed that tumor cells diffusely express CD34, p75, and partially express EMA (cytoplasm), while S-100, Desmin, AE1/AE3, actins, FXIIIa all tested negative." (PMID 38388419, 2024). "In this study, we evaluated mast cell and CD34 microvessel densities in tumor samples from 238 patients with stage I–III LUAD following complete surgical resection, using an immunohistochemical approach." (PMID 38834833, 2024). "State0 (Cd34− CAF) represents a more differentiation state with the tumor-prone signature marker such as Acta2." (PMID 39401181, 2024). "The diagnosis of LPF-NT depends on pathological examination, and immunohistochemical examination of the co-expression of S100 and CD34 helps identify this type of tumor." (PMID 39345656, 2024). "CD34 is a marker of vascular endothelial cells, which can show the distribution of blood vessels in tumor tissue." (PMID 38526656, 2024). "CD34 was negatively expressed in the tumor cells and positively expressed in the vascular endothelium." (PMID 39432588, 2024). "These experiments suggest that in the tumor microenvironment, cytokines secreted by tumor cells inhibit the differentiation of CD34+ bone marrow stem cells into DCs, while negatively regulated DCs increase tumor aggressiveness." (PMID 38381884, 2024). "A TAM population, F4/80+ macrophages, transformed from Kupffer cells, localized around vessels in tumours and expressed key angiogenic markers, including VEGFA, TIE2, and CD34, signifying its essential role in tumour vascularization." (PMID 38303024, 2024). "In the current cohort, CD34 was only expressed in 3/33 (9%) of DTFs with a range of 10 to 30% of positivity in the tumor cells." (PMID 39410565, 2024). "The patient underwent open complete resection of a giant abdominal pelvic tumor with no complications and was diagnosed as SFT according to the pathology, immunohistochemistry showed that the tumor tested positive for CD34(+), STAT-6(+), and Ki-67 (10%)." (PMID 39121255, 2024). "The tumor cells of the five patients included in our current study all positively expressed CD34, and four out of five positively expressed CD31 and ERG, which was consistent with previous literature reports." (PMID 38962269, 2024). "As part of our study, we analyzed POSTN expression in tumor cells and tumor stroma and assessed its association with the pro-angiogenic factors (CD31, CD34, CD105, VEGF-A) in NSCLC." (PMID 39272978, 2024). "All of the clinicopathological data of the patients were similar in the LLR and RLR groups, including gender, age, presentation, tumor location, tumor diameter, histologic type, mitotic count/50HPF, CD117, CD34, risk NIH classification." (PMID 38678296, 2024). "Serial dilutions of engineered fluorescent tumor cells were mixed with either CD4+ or CD34+ primary cells, and their growth was followed." (PMID 39416278, 2024). "We observed strong nuclear and diffuse STAT6 immunoreactivity in tumor cells, along with diffuse positivity for CD34." (PMID 38388450, 2024). "To investigate the identity of the increased VLSs in MOC2CX3CL1 tumors, we immunostained the tumor tissue using the blood vessel marker, CD34, and the LV marker, podoplanin (PDPN)." (PMID 38775151, 2024). "Our research utilized immunofluorescence techniques to gauge Mannose/CD68 and CD34/Mannose expression within tumor cohorts and appraised iNOS/CD68 and Mannose/CD68 expressions in macrophages." (PMID 38967628, 2024). "Immunohistochemically, the tumor is positive for S100, CD34, and SOX-10 and has an H3K27me3 expression deletion." (PMID 39345656, 2024).